ENSG00000308907 (novel transcript)
Gene: Long non-coding RNA gene on chromosome 20 (49,278,642 to 49,279,641, reverse strand). Ensembl gene ENSG00000308907.
Gene Ontology:
Biological process: RNA processing
Cellular component: cytoplasm; nucleolus; nucleus